XIAP (X-linked inhibitor of apoptosis)
Diseases named in the same sentence as XIAP in open-access papers (continued):
Sharing a sentence is not in itself a finding about the gene and the disease.
infection (continued). "Taken altogether, we propose that upon infection, NP occupies hnRNP-C and renders it less available for XIAP translation, thereby indirectly promoting host apoptosis and thus RNP export." (PMID 36362400, 2022). "All pro- (Casp-8, FADD, BAX, and BAK) or anti-apoptotic (BCL-2 and XIAP) genes tested were down regulated at early time points post-SVA infection (2–4 h p.i.)(p < 0.05 when compared to mock-infected cells)." (PMID 30918505, 2019). "Immunoblot analysis confirmed upshift of RIPK2 starting 2 h p.i. in cells treated with a control siRNA and infection independent upshift in cells with reduced XIAP levels." (PMID 31350258, 2019). "By contrast, these mutations blocked Shigella-induced IL-8 secretion and degradation of XIAP upon infection." (PMID 31350258, 2019). "Birinapant treatment enhanced IFNγ-induced expression of iNOS synergistically in infected cells (M1 proteins) at 48 h post infection time interval which was accompanied with the upregulating XIAP proteins." (PMID 29375545, 2017). "Upregulation of cIAP proteins and reduced expression of XIAP proteins during the course of infection revealed a possible compensation of IAP proteins in ciap-1 KO animals." (PMID 29375545, 2017). "Although RIPA is activated early after infection, the anti-apoptotic protein XIAP blocks apoptosis by preventing caspase activation; later in infection, XIAP is degraded and the block to apoptosis is removed." (PMID 27815826, 2017). "Mechanistic validation demonstrated that Gadd45 overexpression or XIAP knockdown enhanced Bax expression, inhibited Bcl-2, increased apoptosis rates, and consequently significantly reduced intracellular bacterial load at 24 h post-infection." (PMID 41011363, 2025). "Translating these findings to in vivo conditions, we postulate that the efficacy of this Gadd45/XIAP-mediated apoptotic defense could be a critical determinant of infection outcome." (PMID 41011363, 2025). "With XIAP deficiency, EBV markedly elevated apoptosis rates over the first 2 weeks of infection." (PMID 40674368, 2025). "While we observed that inhibition of NLRP3 reduced IL-1β secretion during infection with ST, cell death and IL-1β secretion by Xiap−/− cells was still higher than WT cells, suggesting that XIAP inhibits additional cell death pathways to control cell death and IL-1β secretion by APCs." (PMID 37347786, 2023). "To investigate if loss of XIAP plays a role in EBV-infected B cells, we isolated B cells of XIAP patient-derived PBMCs, their mothers, and healthy donor controls and infected them with the EBV B95-8 strain at a multiplicity of infection (MOI) of 0.1." (PMID 36270981, 2022). "Infection with Sendai and vesicular stomatitis virus causes phosphorylation of XIAP at serine 430 by TBK1/IKK in vivo, resulting in auto-ubiquitination-mediated proteasomal destruction of XIAP." (PMID 34718659, 2021). "We also discovered that cells individually lacking AKT1 or AKT2 survive LGTV infection better than WT cells, and this was associated with higher amounts of antiapoptotic XIAP and survivin and increased resistance to LGTV-induced apoptotic cell death." (PMID 32977414, 2020). "In order to investigate the expression of XIAP after Ad-XIAP-GFP infection with BMSCs, the cells infected with Ad-XIAP-GFP and Ad-GFP on the 3rd day and the untreated cells were selected, and the expression of XIAP mRNA and protein was detected by RT-qPCR and western blot analysis." (PMID 31660045, 2019). "Notably, we observed that XIAP levels were reduced upon infection in cells expressing RIPK2, RIPK2 S176A, and RIPK2 S176E but not in cells expressing RIPK2 Y747F and correlated with the induction of RIPosome formation." (PMID 31350258, 2019). "By using S. flexneri as an infection model we could recently demonstrate the physiologic relevance of these findings in vitro and in vivo, underscoring the impact of XIAP on anti-bacterial immunity." (PMID 25187968, 2014).
infection (continued). "Cells were harvested at 48 h after infection, and XIAP expression was analyzed by Western blot." (PMID 23251610, 2012). "Notably, we observed extensive cell death of XIAP-KO cells by day 4 after infection." (PMID 40674368, 2025). "In addition, RNAi KD of XIAP also decreased infection and significantly increased apoptosis." (PMID 37594275, 2023). "Similar to our XIAP CRISPR analyses, proliferation of XLP-2 cells was diminished over the first week of infection relative to healthy controls." (PMID 40674368, 2025). "We generated Xiap−/− OT1 TCR transgenic mice and evaluated the role of XIAP in the expansion and contraction of CD8 T cell response during infection with Salmonella enterica serovar Typhimurium (ST) and Listeria monocytogenes (LM)." (PMID 37347786, 2023). "XIAP is maintained at high levels in LVS-infected PMNs via increased expression of the BIRC4 gene and by upregulation of calpastatin (CAST), which prevents calpain-mediated XIAP degradation in healthy cells and during LVS infection." (PMID 35873156, 2022). "Our datasets confirm several previously demonstrated PTMs that occur in response to infection, such as elevated phosphorylation of RIPK1 at S321, XIAP at S429 or IRF3 on multiple sites." (PMID 34085925, 2021). "In the absence of XIAP, myeloid cells are particularly prone to cell death in response to infection." (PMID 36270981, 2022). "There was no significant change for the protein levels of cIAP1, XIAP, and Survivin during the course of infection." (PMID 32820150, 2020). "Interestingly, XIAP levels were preserved and S176 phosphorylation increased in the course of S. flexneri M90T infection when cells were pretreated with GSK583, whereas gefitinib led to reduced XIAP and pS176 levels." (PMID 31350258, 2019). "This is supported by our previous findings that expression of cIAP-1, XIAP, and survivin are all decreased by P/V-CPI- infection and that chemical inhibition of survivin (with YM155) or XIAP (with Embelin) enhanced killing of a P/V-CPI- persistently infected cell line." (PMID 31083335, 2019). "XIAP depletion alone in humans leads to disease but XIAP−/− mice are in most aspects normal, although they can be induced to develop disease similar to XLP-2 in humans by infection with a herpes virus, MHV-6838." (PMID 29743550, 2018). "Expression of the gene for the X-linked inhibitor of apoptosis (XIAP), another IAP family member, was not significantly differentially altered after infection (data not shown)." (PMID 26792742, 2016). "To address how caspase-3 is not activated by infection-induced activated caspase-9, we first analyzed expression of genes encoding inhibitors of apoptosis protein IAP1, IAP2, and XIAP." (PMID 26290316, 2015). "However, murine infection models clearly show that XIAP has a critical role in innate immunity and the clinical data on XLP2 patients implicate XIAP function in immune regulation." (PMID 23818254, 2013). "For example, although STAT3 modulates cleavage of caspase 3 during infection, the apoptotic pressure elicited by STAT3 inhibition may be insufficient to outweigh the effect of XIAP stabilization, which acts downstream of other anti-apoptotic mechanisms, such as BCL-2 family proteins." (PMID 41115066, 2025). "We considered the possibility that the enhanced cell death of Xiap−/− APCs might be responsible for reduced priming of CD8 T cells, however, we did not observe any impact of XIAP on cell death in response to infection with LM-OVA." (PMID 37347786, 2023). "Infection of macrophages with log-phase ST did not reveal any impact of XIAP on cell death." (PMID 37347786, 2023).
infection (continued). "Previously XIAP was shown to have no impact on CD8 T cell response evaluated on day 7/8 of infection with Lymphocytic Choriomeningitis Virus (LCMV), and treatment of mice with an inhibitor that blocks all IAPs resulted in reduced numbers of antigen specific CD8 T cells." (PMID 37347786, 2023). "With the X-linked inhibitor of apoptosis (XIAP) known to transnitrosylate caspase-3, and vice versa, it is possible that inhibition of this XIAP reaction may also be targeted by AIEC in a similar fashion to Pseudomonas aeruginosa which stabilizes XIAP and delays apoptosis during infection." (PMID 23861899, 2013). "Importantly, infection of neither ZD55-Sur-EGFP nor AD-Sur-EGFP affected the expression of another anti-apoptotic protein XIAP." (PMID 19527508, 2009). "Infection of AGS cells with H. pylori for 1 h dramatically increased the expression of BIRC3 (gene of cIAP2), but not the expression of BIRC2 (gene of cIAP1), BIRC4 (gene of XIAP), BIRC5 (gene of Survivin) and other apoptosis related genes." (PMID 32820150, 2020).
hematological cancers (5 papers, 2015 to 2021). "DMF was also identified to induce apoptosis of hematopoietic cancer cells by inactivating NF-κB and down-regulating Bcl-XL and XIAP expression." (PMID 33692690, 2021).
bacterial infection (4 papers, 2008 to 2021). "To better define the role of XIAP during innate immunity to intracellular bacterial infection, we infected wild-type and XIAP-deficient mice intraperitoneally with 5×105L." (PMID 18769721, 2008). "Indeed, in mice deficient for XIAP, certain bacterial infections are unable to be cleared and cells are incapable of activating both the NOD2- and XIAP-mediated NF-κB survival pathways." (PMID 30389919, 2018). "Activation of either NOD1 or NOD2 activates TAK1, leading us to hypothesize that during bacterial infection, XIAP may facilitate this key association, linking cytosolic sensors to downstream signaling mediators." (PMID 18769721, 2008). "We noticed that XIAP levels also declined upon bacterial infection and that this coincided with RIPK2 upshift, suggesting that XIAP activity and protein abundance negatively regulate RIPosome formation." (PMID 31350258, 2019). "Depending upon the inoculum, morbidity and mortality of xiap−/y animals occurred between 2 and 5 dpi, prior to peak development of adaptive immunity, suggesting that XIAP had a protective effect during the innate response to bacterial infection." (PMID 18769721, 2008). "As XIAP depletion induced sterile RIPosome formation, this suggests that XIAP might be central in controlling RIPosome formation also upon bacterial infection." (PMID 31350258, 2019). "Additionally, XIAP promoted maximal production of pro-inflammatory cytokines upon bacterial infection in vitro or in vivo, or in response to combined treatment with NOD2 and TLR2 ligands." (PMID 18769721, 2008). "However, JNK phosphorylation in response to vacuolar bacteria quickly diminished after 30 min, in contrast to the extended XIAP-dependent JNK activation observed during wild-type bacterial infection." (PMID 18769721, 2008). "At 1 and 2 hpi, infected xiap+/y macrophage nuclear lysates contained significantly more NF-κB DNA binding activity than infected xiap−/y nuclear lysates, suggesting that XIAP might enhance signaling of NF-κB–dependent pathways stimulated by bacterial infection." (PMID 18769721, 2008).
breast (4 papers, 2010 to 2023). "High levels of TRAIL decoy receptor expression are associated with poor prognosis and resistance to 5-fluorouracil or oxaliplatin and to increased levels of anti-apoptotic proteins survivin and XIAP in metastatic colorectal cell lines." (PMID 20068564, 2010). "Additionally, XIAP-positive patients showed better survival in the lymph node-negative population (48.4 vs. 24.2 months, p = 0.019)." (PMID 36472768, 2023).
adenocarcinoma (3 papers, 2015 to 2023). A common cancer characterized by the presence of malignant glandular cells. "XIAP mRNA is overexpressed in all adenocarcinoma cell lines as compared to Caco-2, mostly in SW620 (over 6-fold) (lane 4) and in HT29 and Colo205 (up to 4-fold) (lanes 5 and 7, respectively)." (PMID 27520705, 2016). "XIAP, DR4 and DR5 are overexpressed at the mRNA and protein levels in all adenocarcinoma cell lines." (PMID 27520705, 2016).
metabolic disorders (3 papers, 2019 to 2025). "Notably, siXIAP-treated mice exhibited higher glucose levels and dramatic shifts in area under curve (AUC) scores, suggesting that knockdown of XIAP in vivo may impair glucose tolerance and insulin sensitivity, further exacerbating metabolic disorders." (PMID 31841118, 2019). "In addition, knockdown of XIAP in vivo may result in a further increase in mouse body weight, as previous studies have demonstrated that a prolonged HFD significantly contributed to the development of metabolic disorder." (PMID 31841118, 2019).
neurodegenerative disease (3 papers, 2013 to 2023). A disorder of the central nervous system characterized by gradual and progressive loss of neural tissue and neurologic function. "The X-linked inhibitor of apoptosis (XIAP) protein is the principal cellular caspase inhibitor among the IAPs, and it is S-nitrosylated in various neurodegenerative diseases." (PMID 35204298, 2022).
inflammation (2 papers, 2017 to 2019). Aberrant reaction of the microcirculation characterized by movement of fluid and leukocytes from the blood into extravascular tissues. "To further investigate whether defects in bacterial handling are commonly related to granulomatous intestinal inflammation, we studied individuals with loss-of-function mutations in XIAP." (PMID 26953272, 2017).
neurological diseases (2 papers, 2012 to 2014). "S-nitrosylation of Parkin, protein disulfide isomerase (PDI), peroxiredoxin 2 (Prx2), X-linked inhibitor of apoptosis (XIAP), and Drp1 has been implicated in stress-induced neuronal death and has been also observed in brains from patients with neurological disorders." (PMID 22927857, 2012).
intestinal diseases (1 paper, 2023).
XIAP also shares sentences with these, for which no sentence is quoted: hematological malignancies (11 papers); multiple myeloma (7); graft versus host disease (5); Cognitive impairment (3); common variable immunodeficiency (3); genetic disorders (3); head and neck squamous cell carcinoma (3); lymphoproliferative disorder (3); Wiskott-Aldrich syndrome (3); acute kidney injury (2); acute leukemia (2); adult-onset Still disease (2); Alzheimer disease (2); and Cutaneous T-Cell Lymphoma (2); Autoimmunity (2); chronic leukemia (2); familial Mediterranean fever (2); Hyperglycemia (2); IPEX syndrome (2); mantle cell lymphoma (2); nasopharyngeal carcinoma (2); Noonan-like syndrome (2); polyendocrinopathy (2); ulcerative colitis (2); -neck cancer (1); 22q11.2 deletion syndrome (1); acquired immunodeficiencies (1); acute GVHD (1); acute respiratory distress syndrome (1); AIDS (1).
A further 82 diseases each share a sentence with XIAP in 1 paper.